DKC1 (dyskerin pseudouridine synthase 1)
Diseases named in the same sentence as DKC1 in open-access papers (continued):
Sharing a sentence is not in itself a finding about the gene and the disease.
colorectal cancer (continued). "DKC1 overexpression has been reported in many cancers, including neuroblastoma, lymphoma, melanoma, colorectal cancer, ovarian carcinoma, breast cancer and hepatocellular carcinoma, and often results in poor prognosis due to aggressive tumor growth and resistance to therapy." (PMID 33599797, 2021). "However, the expression and function of DKC1 in colorectal cancer (CRC) is rarely reported." (PMID 31857720, 2020). "DKC1 has been shown to regulate the NF-κB/MMP-2 pathway in ccRCC, and improve HIF-1α transcription levels by binding its promoter region in colorectal cancer." (PMID 38082360, 2023). "To further validate the correlation of DKC1 with CD8+ T cells, we collected colorectal cancer tissues and immunohistochemically stained the expression of CD8 and DKC1." (PMID 36428700, 2022). "Taken together, these results suggested that DKC1, CSE1L and NSUN5 were dramatically overexpressed while FLNA was significantly downregulated in colorectal cancer." (PMID 36319976, 2022). "As for the molecular mechanism of PUS involvement in cancer, it has been reported that overexpression of DKC1 increased the expression of TERC and rRNA pseudouridylation, promoting the proliferation of colorectal cancer." (PMID 36437949, 2022). "The combination of the DKC1 inhibitor pyrazofurin (PF) and the MEK1/2 inhibitor trametinib synergistically suppressed colorectal cancer growth." (PMID 34026451, 2021). "The pyrazofurin (DKC1 inhibitor) and trametinib (MEK inhibitor) combination synergistically restrains colorectal cancer cell growth." (PMID 34026451, 2021). "Based on these findings, dual inhibition of DKC1 and MEK1/2 synergistically suppressed the growth of colorectal cancer cells both in vivo and in vitro, which may be of benefit for future clinical trials to treat CRC patients with DKC1 overexpression." (PMID 34026451, 2021). "At the same time, DKC1‐targeted ribosomal proteins suppressed the RAS/RAF/MEK/ERK pathway via interaction with HRAS, and combination therapy with PF and trametinib exhibited synergistic anticancer efficacy in colorectal cancer cells." (PMID 34026451, 2021). "Notably, the DKC1 inhibitor pyrazofurin and the MEK1/2 inhibitor trametinib can synergistically suppress colorectal cancer growth, suggesting the Ψ synthases are very promising therapeutic targets for cancer." (PMID 35118063, 2021).
neuroblastoma (12 papers, 2008 to 2025). Neuroblastoma (NB) is the most common solid, extracranial childhood tumor. "In neuroblastoma, both N-Myc and C-Myc have been reported to directly target the DKC1 promoter, resulting in elevated DKC1 mRNA expression levels." (PMID 39162904, 2024). "The results showed that the mRNA and protein levels of DKC1 in five neuroblastoma cells were significantly higher than those in CHP-126 cells, especially in CHP-134 and LAN-1 cells." (PMID 37426487, 2023). "In this study, the gene congenital dyskeratosis 1 (DKC1) related to the survival analysis of neuroblastoma was screened from TCGA tumor database by data mining." (PMID 37426487, 2023). "The mRNA and protein expression levels of DKC1 in tumor tissues and adjacent tissues of 12 clinical neuroblastoma cases were detected." (PMID 37426487, 2023). "In conclusion, the high expression of DKC1 in neuroblastoma can regulate the proliferation, apoptosis, invasion, and metastasis of neuroblastoma." (PMID 37426487, 2023). "DKC1 expression, including mRNA level and protein level, was detected in human neuroblastoma cell line CHP-126 and five neuroblastoma cell lines CHP-134, SH-SY5Y, SK-N-SH, LAN-1, and IMR-32." (PMID 37426487, 2023). "miRNA326-5p targeting DKC1 mRNA regulates apoptosis-related proteins to inhibit neuroblastoma proliferation and promote the apoptotic process." (PMID 37426487, 2023). "However, SNHG25 was proven to function through interaction with protein dyskerin pseudouridine synthase 1 (DKC1) in neuroblastoma cells." (PMID 41387767, 2025). "Therefore, we explored the mechanism of DKC1 in neuroblastoma through in vitro and in vivo experiments, in order to provide a new target for the treatment of neuroblastoma." (PMID 37426487, 2023). "The expression and function of DKC1 in neuroblastoma are rarely reported." (PMID 37426487, 2023). "We speculated that DKC1 could regulate Bcl-2 family proteins in neuroblastoma and control the internal apoptosis pathway of tumor cells." (PMID 37426487, 2023). "The expression of DKC1 in neuroblastoma was analyzed by TCGA database and molecular assay." (PMID 37426487, 2023). "After DKC1 was knocked out, the apoptosis of neuroblastoma cells was significantly increased." (PMID 37426487, 2023). "Depletion of DKC1 in neuroblastoma cells reduced cell growth." (PMID 33599797, 2021). "The high expression of DKC1 in tumors suggests that it may be closely related to neuroblastoma." (PMID 37426487, 2023). "Therefore, DKC1 may be involved in the molecular mechanism of neuroblastoma cell proliferation, apoptosis, invasion, and migration." (PMID 37426487, 2023). "In MYC-amplified neuroblastoma cells, n-MYC and c-MYC bind to the proximal DKC1 promoter and drive the expression of DKC1 gene." (PMID 33599797, 2021). "Because increased activity of MYCN in stage 4s-NA or c-MYC in stage 4-NA tumors should both result in high expression of shared target genes compared to localized-NA neuroblastomas, we analyzed known direct MYCN/c-MYC target genes, namely MDM2, DKC1, and PTMA, in neuroblastoma subtypes." (PMID 18851746, 2008).
bone marrow failure (9 papers, 2011 to 2024). "X-DC is caused by mutations in the DKC1 gene and is characterized by bone marrow failure, ribosomal dysfunction, and increased susceptibility to cancer." (PMID 28054974, 2017). "X-linked DC is caused by mutations in DKC1, are characterized by bone marrow failure and increased susceptibility to cancer." (PMID 21931644, 2011). "Furthermore, mice deficient in DKC1 develop hematopoietic symptoms including bone marrow failure, anemia, decreased hemoglobin content, etc.." (PMID 34315813, 2021). "Mutations in DKC1 causes premature aging, bone marrow failure, and cancer." (PMID 31921313, 2019).
hepatocellular carcinoma (9 papers, 2012 to 2023). A malignant tumor that arises from hepatocytes. "Also, in hepatocellular carcinoma DKC1 overexpression was an independent risk factor for the prognosis of the disease." (PMID 26366868, 2015). "Hepatocellular carcinoma, breast cancer, prostate cancer, colorectal cancer, and lung cancer express DKC1 at high levels, and its expression is related to disease progression and prognosis." (PMID 37420297, 2023). "Moreover, the expression of DKC1 was demonstrated to be elevated in hepatocellular carcinoma (HCC) and associated with a poor prognosis of HCC patients." (PMID 37188742, 2023). "More recently, DKC1 was found to promote proliferation, survival, invasion and metastasis of colorectal and hepatocellular cancer cells by enhancing HIF-1α expression and antioxidative effect, respectively." (PMID 37434223, 2023). "In addition, a significant DKC1 upregulation was detected in different types of solid tumors, including hepatocellular carcinoma, prostate, colon, and breast cancer, suggesting a critical role for this gene in carcinogenesis." (PMID 26366868, 2015).
pulmonary fibrosis (8 papers, 2018 to 2025). Chronic progressive interstitial lung disorder characterized by the replacement of the lung tissue by connective tissue, leading to progressive dyspnea, respiratory failure, or right heart failure. "An association between short telomere length, telomere related gene mutations and pulmonary fibrosis was reported in 2005 when a DKC1 mutation was first described." (PMID 35203522, 2022). "Mutations in telomerase complex genes such as Tert, Terc, RTEL1, PARN or DKC1 are found to be associated with a higher risk of pulmonary fibrosis." (PMID 31248154, 2019). "The subject of DKC1 product’s involvement in fibrosis, and lung fibrosis in particular, requires further investigation." (PMID 31248154, 2019). "Hypomorphic Dkc1 mutant mice show lung abnormalities, including abnormal morphology of the pulmonary parenchyma, alveolus and alveolus wall, lung inflammation and pulmonary interstitial fibrosis." (PMID 29383478, 2018). "In 1995, the first link between DKC1 and pulmonary fibrosis was found in 46 families recruited at Hammersmith Hospital which occurs in 19% of cases and is a congenital telomere disease characterized by skin abnormalities, bone marrow failure, and lung fibrosis." (PMID 36860670, 2023).
Hoyeraal-Hreidarsson syndrome (7 papers, 2017 to 2023). Hoyeraal-Hreidarsson syndrome (HHS) is a very rare X-linked recessive disorder considered to be a severe variant of dyskeratosis congenita characterized by intrauterine growth retardation, microcephaly, cerebellar hypoplasia, progressive combined immune deficiency and aplastic anemia. "Mutation of dyskerin pseudouridine synthase 1 (DKC1) frequently result in Hoyeraal-Hreidarsson syndrome, a microcephaly disease." (PMID 37408531, 2023). "The most severe form of DC, Hoyeraal-Hreidarsson syndrome, is caused by mutations to the catalytic domain of dyskerin (DKC1), suggesting that telomere-independent mechanisms contribute to DC." (PMID 33987182, 2021). "In most cases of Hoyeraal-Hreidarsson syndrome, the variant A353V located in the PUA domain of DKC1 is observed." (PMID 37408531, 2023). "Both Hoyeraal-Hreidarsson syndrome patients and mouse models for DKC1 dysfunction show reduced rRNA processing and telomerase activities." (PMID 37408531, 2023).
lung cancer (7 papers, 2015 to 2024). A malignant neoplasm involving the lung. "Similarly, in lung cancer, low DKC1 expression levels were linked to poor FP, OS, and PPS prognosis." (PMID 38082360, 2023). "Our research indicated that DKC1 is a promising target for telomerase-based therapies in lung cancer." (PMID 33879171, 2021). "DKC1 downregulation inhibits telomerase activity, induces telomere length shorten in lung cancer cells." (PMID 33879171, 2021). "On the other hand, in DKC1 hypomorphic mouse, the only DC animal model available to date, an increase in breast and lung cancer occurrence has been described, which seems to be independent from telomere shortening, since it occurs when telomeres are still very long." (PMID 26301749, 2015). "However, whether DKC1 promotes cancer cell growth in lung cancer and whether DKC1′s oncogenic function is dependent on the regulation of telomere remain largely unknown." (PMID 33879171, 2021). "In addition, because of the known role of dyskerin on TERC stabilization, we wondered how TERC levels might be influenced by a conjunct effect of TERC locus amplification and DKC1 expression in lung cancers." (PMID 26301749, 2015). "In lung cancer (LUAD, LUSC), DKC1, PUS1, PUS3, PUS7, TRUB1, and TRUB2 expression was mostly negatively correlated with immune cell infiltration." (PMID 39162904, 2024). "DKC1 and GAR1 were also expressed at high levels in lung cancer samples." (PMID 33288886, 2021).
lung adenocarcinoma (6 papers, 2020 to 2024). A carcinoma that arises from the lung and is characterized by the presence of malignant glandular epithelial cells. "In addition, inhibition of DKC1 induced telomere-associated senescence and apoptosis in lung adenocarcinoma cells." (PMID 39162904, 2024). "We found that DKC1 was significantly upregulated in several cancers, such as lung adenocarcinoma (LUAD), liver hepatocellular carcinoma (LIHC), and breast invasive carcinoma (BRCA), and exhibited widespread upregulation across different cancer types." (PMID 39103487, 2024). "Elevated DKC1 expression in other tumor types such as lung adenocarcinoma or head and neck SCC (HNSCC) correlated with disease progression, according to previous studies." (PMID 36732018, 2023). "In conclusion, our data suggest that high expression of DKC1 could act as a candidate marker for diagnosis and therapy target in lung adenocarcinoma by inducing telomere-related cell senescence and apoptosis." (PMID 33879171, 2021).
liver cancer (5 papers, 2021 to 2025). An epithelial or non-epithelial malignant neoplasm that arises from the liver. "Recent studies unravel that DKC1 promotes proliferation, survival, invasion or metastasis of colon and liver cancer cells by increasing HIF-1α expression and antioxidative effect, respectively." (PMID 40458122, 2025). "The results showed that high DKC1 expression levels were associated with poor OS, PFS, RFS, and DSS prognosis in liver cancer." (PMID 38082360, 2023).
colon carcinoma (4 papers, 2020 to 2023). "miR-197-3p overexpression augmented the oxaliplatin resistance of colon carcinoma by inhibiting DKC1." (PMID 36769824, 2023). "After 48 h, DKC1 protein and mRNA levels were knocked down in the two colon cancer cells (respectively)." (PMID 31857720, 2020). "To elucidate the role of the DKC1 in colon cancer cells, we investigated its role in colon cancer cell migration and invasion." (PMID 31857720, 2020). "DKC1 expression was positively correlated with the macrophages marker, CD68, at the invasive front of colon cancer tumors." (PMID 36428700, 2022). "The mRNA levels of DKC1, CSE1L and NSUN5 were higher in the colon cancer tissues than in the paired adjacent normal tissues, while the level of FLNA was lower (p < 0.05)." (PMID 36319976, 2022).
bone marrow failure syndrome (3 papers, 2011 to 2023). "Through mutation screening in patients with DC and related bone marrow failure syndromes, we have identified 23 novel mutations in core components of telomerase: 11 in TERC, 8 in TERT and 4 in DKC1." (PMID 21931702, 2011).
Breast Invasive Carcinoma (3 papers, 2020 to 2024). "The association among DKC1 mRNA levels and patient prognosis was further confirmed in a larger series from the Pan-Cancer study (Breast Invasive Carcinoma TCGA PanCancer dataset available online)." (PMID 33255756, 2020). "The analysis of the TCGA breast invasive carcinomas dataset by GEPIA2 indicated that the identified molecular signature is significantly related to DKC1 expression also in this dataset." (PMID 35996163, 2022).
gastric cancer (3 papers, 2023 to 2026). A primary or metastatic malignant neoplasm involving the stomach. "However, in gastric cancer, low DKC1 expression levels were associated with poor FP, OS, and PPS prognosis." (PMID 38082360, 2023).
glioblastoma (3 papers, 2022 to 2025). The most malignant astrocytic tumor (WHO grade IV). "For example, DKC1, which is elevated in glioblastoma, correlates with WHO grade and a poor prognosis of glioblastoma." (PMID 36012529, 2022).
melanoma (3 papers, 2017 to 2023). A malignant, usually aggressive tumor composed of atypical, neoplastic melanocytes. "Thus, different from melanoma, mechanisms underlying sex-specific effects in ccRCC are more complicated, and likely involved in interactions among many more signaling pathways including DKC1." (PMID 37434223, 2023). "Interestingly, DKC1 (and partly also RUVBL2) overexpression associates consistently with unfavorable prognosis in renal, liver, head-neck, endometrial and skin (melanoma) cancers." (PMID 31750255, 2019).
ovarian carcinoma (3 papers, 2022 to 2023). A malignant neoplasm originating from the surface ovarian epithelium. "In ovarian cancer, low DKC1 expression was also linked to poor OS, PFS, and PPS prognosis." (PMID 38082360, 2023). "However, in lung SCC and ovarian cancer low DKC1 expression levels were associated with poor survival rates and had been also reported in endometrial cancer." (PMID 36732018, 2023). "Silencing DKC1 expression in SNORA70E stably overexpressing ovarian cancer cells inhibited the increased cell proliferation and migration ability." (PMID 36056690, 2022). "Results showed that the expression level of DKC1 protein was upregulated in BRCA, Ovarian cancer, LUAD, COAD, HNSC, UCEC, ccRCC and HCC, but downregulated significantly in Pancreatic adenocarcinoma compared with that in normal tissues." (PMID 38082360, 2023).
pituitary adenomas (3 papers, 2017 to 2024). "A novel mutation (DKC1S485G) in DKC1 found in human pituitary adenomas has been shown to significantly impact DKC1 stability and pseudouridylation activity, leading to decreased p27 protein levels." (PMID 39737343, 2024). "In 2010, the same group, headed by Davide Ruggero, showed that DKC1 is mutated in pituitary adenoma and that this genotype causes a defect in pseudouridylation activity and reduced expression of p27." (PMID 32241281, 2020). "Finally, they found a DKC1 mutation in patients with pituitary adenoma that drastically reduced DKC1 expression and pseudouridylation, but also brought about a reduction in p27 expression." (PMID 32241281, 2020).
breast tumors (2 papers, 2020 to 2023). "Paradoxically, DKC1 overexpression correlates with disease progression and poor prognosis in many sporadic cancers, such as prostate and breast tumors, and DKC1 levels also associate with higher levels of TERC expression and telomerase activity in some of these tumors." (PMID 36732018, 2023). "Our results also showed positive correlations between nuclear and nucleolar DKC1 protein expression in the breast tumour cells." (PMID 32868896, 2020).
chronic lymphocytic leukaemia (2 papers, 2009 to 2017). "Moreover, in sporadic chronic lymphocytic leukaemia, DKC1 expression is diminished, together with that of other telomerase-associated factors." (PMID 19755982, 2009). "In this study, we have evaluated the expression profile of the H/ACA RNP complex genes: DKC1, NOP10, NHP2 and GAR1, as well as hTERT and hTR mRNA levels, in patients with chronic lymphocytic leukemia (CLL)." (PMID 28666010, 2017).
clear cell renal cell carcinoma (2 papers, 2020 to 2025). "DKC1 is highly expressed in clear cell renal cell carcinoma." (PMID 32528520, 2020). "However, genomic analyses in clear cell renal cell carcinoma (CCRCC) have revealed that female patients with elevated DKC1 expression also exhibit increased TERC levels, a pattern associated with reduced therapeutic response and shorter progression-free survival." (PMID 40642018, 2025).
Fanconi anaemia (2 papers, 2013 to 2025). "At our single institution, we had a yield of 14% (6/43) for patients with MDS or AML who were found to have a PV predisposing to myeloid disease (Fanconi Anemia, DKC1, DDX41, GATA2, TERC, and RUNX1)." (PMID 40936482, 2025). "We have identified signatures of positive selection acting within regions of the genes directly involved in telomere maintenance in M. lucifugus (DKC1 and TERT) and within the Fanconi anaemia/BRCA pathway DNA repair pathway in naked mole rat." (PMID 24237966, 2013).
idiopathic pulmonary fibrosis (2 papers, 2019 to 2025). Idiopathic pulmonary fibrosis (IPF) is a nonneoplastic pulmonary disease that is characterized by the formation of scar tissue within the lungs in the absence of any known cause. "She went on to identify additional families who suffered from DC who had mutations in the gene DKC1, which also encodes for a component of telomerase, and who later developed idiopathic pulmonary fibrosis (IPF)." (PMID 40095034, 2025).
leukopenia (2 papers, 2021 to 2025). "A patient with recurrent aphthous stomatitis and mild leukopenia was found to have a DKC1 variant, leading to a diagnosis of DC and implementation of malignancy surveillance." (PMID 40358701, 2025).